KRAS (KRas proto-oncogene, GTPase)
Diseases named in the same sentence as KRAS in open-access papers (continued):
Sharing a sentence is not in itself a finding about the gene and the disease.
tumor (continued). "Dysregulation of KRAS resulting from point mutations can directly affect downstream signaling pathways, especially the PI3K/Akt and MAPK pathways, thus leading to abnormal tumor growth." (PMID 36508072, 2022). "In addition, the feasibility of interfering with effector binding was demonstrated by engineering a cell‐permeable RAS‐binding domain polypeptide that achieved potent and selective anti‐tumor effects in KRAS mutant cell lines." (PMID 34951114, 2022). "In MSI-high cases, the use of NSAIDs was associated with over a 70% risk reduction in KRAS- or BRAF-WT tumours, but no reductions were found in KRAS- or BRAF-mutant cases." (PMID 35764787, 2022). "In addition, oncogenic KRAS has been shown to promote tumor signaling through metabolic reprogramming and stromal interactions to facilitate tumor growth." (PMID 36408139, 2022). "To examine the association of the signature with the clinicopathological characteristics of CRC, we determined the correlation between the signature and different clinical characteristics of CRC (age, sex, tumor location, TNM stage, KRAS mutation, and BRAF mutation)." (PMID 35350786, 2022). "Knocking out KRAS (the most common gene mutation in 95% PDA patients) in cancer cells even made insulin lose the ability to promote cancer cell viability, and insulin even turned to induced tumor cell dormancy in vitro experiments." (PMID 35252207, 2022). "However, it is also capable of producing oncogenic KRAS-specific IgG, which can contribute to an anti-tumour antibody treatment response." (PMID 35205769, 2022). "The KRAS oncogene has been extensively studied in human tumor malignancies." (PMID 34489556, 2022). "In addition, in tumor xenografts, unligated integrin αvβ3 interacts with galectin-3 at the plasma membrane, resulting in recruitment of KRAS and RalB." (PMID 35763345, 2022). "Furthermore, SHP-2 inhibition resulted in a higher cell senescence and lower grade of tumor development in preclinical models of KRAS mutant NSCLC, with a synergistic effect observed when combining adagrasib with the anti-SHP-2 agent RMC-4550." (PMID 36358848, 2022). "However, the relationship between PI3K and tumor cells evading KRAS inhibition still requires further study." (PMID 36291766, 2022). "Furthermore, the silencing of GFPT2 expression inhibited the cell growth and tumor survival in KRAS/LKB1-co-mutant H460 and H2122 cells and co-mutant mice." (PMID 36532721, 2022). "Taken together, MBOAT2 overexpression may interact with KRAS activation, promoting tumor progression and inhibiting the antitumor effect of CD8+ T-cells in PC." (PMID 35571489, 2022). "Changes in KRAS (KRAS∗) are found in virtually all PDAC cases and are linked to tumor survival." (PMID 36046825, 2022). "Importantly, KRAS can cause immunosuppression in CRC, allowing for tumor progression through inhibiting interferon regulatory factor 2 (IRF2), which results in an increase in the expression of MDSCs, supporting their migration to TME." (PMID 36430176, 2022). "In addition, a transgenic zebrafish for liver cancer overexpressing the oncogene KRAS was used to study the effects of environmental toxicants on tumor development and inflammatory response." (PMID 35565373, 2022). "Low FDG uptake is due to various reasons, including low glucose metabolism, low cellularity or small tumor size, recent chemotherapy, and absence of KRAS mutations." (PMID 36551738, 2022).
tumor (continued). "Mutant KRAS (mKRAS) could also drive tumor-intrinsic granulocyte macrophage colony-stimulating factor (GM-CSF) and chemokine C-X-C motif ligand 1 (CXCL1) expression, promoting MDSC infiltration." (PMID 35433680, 2022). "Of these patients, P001, P002, P006, and P007 all had a detectable KRAS G12D mutation in tumor tissue while P004 did not have any mutation present." (PMID 35448266, 2022). "High KRAS expression was significantly associated with poorly differentiated OSCC (grade 3; P<0.001), higher tumor extent (P=0.001), the presence of nodal (P≤0.001) and distant metastasis (P=0.009), higher pathological stage (P<0.001), and the presence of lymphovascular invasion (P<0.001)." (PMID 36532636, 2022). "KRAS-Mut tumors showed significant upregulation of tumor migration (TGFBR2-S553 and EPHB3) and PI3K/AKT activation (PIP4K2C and PIK3R1), while the KRAS-WT group was enriched in immune regulation (TAP1/2, IFITM1, and IFIH1-S301) and cellular metabolism (DGAT1 and HINT3)." (PMID 35836817, 2022). "Likewise, in mice, the behaviour of clones expressing an oncogenic form of KRAS and mutants for the Fbw7 tumour suppressor depends on their location within pancreatic ducts." (PMID 35955754, 2022). "To assess whether we could detect ARS1620-derived epitopes in KRAS G12C tumor xenografts, we treated nude mice bearing xenografts of H358 cells with ARS1620 (200 mg/kg, once daily) and analyzed dissected tumor tissue after 24 h or 72 h." (PMID 36099883, 2022). "Mutated KRAS oncogene promotes tumour progression and metastasis in many preclinical models, but the mutational status of KRAS is not reliably associated with outcome in clinical datasets." (PMID 36163168, 2022). "Thus, molecular quantification of mutant KRAS in tumour tissues is in agreement with expected results." (PMID 35194118, 2022). "The pathological stage was T4N0M0, and KRAS G12D was also detected in the resected tumor." (PMID 35545933, 2022). "We have confirmed the KRAS mutations of the primary tumor in all patients, but Nakamura's study did not describe the KRAS status of the primary tumor." (PMID 35312176, 2022). "Moreover, activated KRAS is observed to contribute to tumor stemness and invasiveness post-radiation therapy, making it a potential therapeutic target in recurring GBMs." (PMID 35664781, 2022). "KRAS G12C inhibitors sequestrated tumor cells in a quiescent state (G0)." (PMID 35267628, 2022). "The induction of the autophagy process maintains tumor cell development and, consequently, the suppression of KRAS and HRAS could slow down the tumor progression and proliferation partially via autophagy inhibition." (PMID 36497321, 2022). "There was also a significantly increased hazard for patients with a canonical KRAS variation: patients whose tumor carried a canonical KRAS variation had increased likelihood of death compared with those without KRAS variation (HR, 1.45; 95% CI, 1.16-1.82) (eTable 4, eFigure 4 in the Supplement)." (PMID 36239938, 2022). "Although inactivation of Rbm10, Rb1, or Apc did have similar effects on EGFR and KRAS mutant tumor growth, Serine/threonine kinase 11 (Stk11, also known as Lkb1) and SET domain containing 2, histone lysine methyltransferase (Setd2) inactivation had opposite effects in the two oncogenic settings." (PMID 35252550, 2022). "This intratumor heterogeneity could explain the relatively lower response of KRAS inhibitors, as they may target only a subtype of tumor cells." (PMID 35205778, 2022).
tumor (continued). "The resistance of KRAS‐mutant tumour cells to alterations in EGFR signalling might result in the null association between hPDI and KRAS‐mutant CRC." (PMID 35998061, 2022). "In a phase 2 study the addition of the specific MET inhibitor tivantinib to cetuximab allowed only 10% of MET-high, KRAS-wt mCRC patients to achieve objective response, even though in a difficult-to-treat setting (tumor progression on cetuximab or panitumumab after a first-line chemotherapy)." (PMID 35582524, 2022). "WES identified KRAS, BRAF, and NRAS mutations in a total of 27 tumours (93%)." (PMID 35715628, 2022). "With multiple KRAS G12C inhibitors in clinical use or undergoing clinical trials, our results present a strategy to enhance their efficacy and overcome the rapidly arising tumor resistance." (PMID 36099883, 2022). "By overexpressing KRAS in cells, the authors restore normal tumor growth." (PMID 35406582, 2022). "The data support that KRAS pathway alterations are marked targets for therapy in a subset of patients with MPM, either as first-line therapy if they truly present tumor-initiating mutations, or as second-line therapy if they drive therapy-resistant KRAS-driven MPM subclones." (PMID 36077838, 2022). "Development of more potent and brain-penetrant KRAS G12C inhibitors could prolong tumor suppression and provide improved PFS, as well as the most efficacious combination partner with such inhibitors." (PMID 35267628, 2022). "KRAS-activated cells could develop into ADCs when Runx3-mediated tumor suppress signaling pathways are abrogated." (PMID 36619616, 2022). "Cancer vaccines provide tumor-specific treatment opportunities for KRAS-driven carcinogenicity." (PMID 35014625, 2022). "In an effort to understand real-world practices involving key clinical issues, physicians were questioned on: (a) Specific tests ordered for molecular diagnostics and (b) the impact of tumor sidedness on their first-line targeted therapy choice for patients with KRAS wildtype." (PMID 36005180, 2022). "In a phase 1b study, the addition of the oral MEK inhibitor binimetinib to the treatment combination of cisplatin and pemetrexed as first-line therapy in advanced KRAS-mutated metastatic NSCLC showed no signal of anti-tumor activity in terms of PFS or OS." (PMID 36077640, 2022). "In the CRC102 model (KRAS G12V MT), the AZD0156/irinotecan doublet (P = 0.0203) and AZD0156/irinotecan/5FU triple combination (P = 0.0090) were again associated with a statistically significant reduction in tumor volume when compared to single-agent AZD0156." (PMID 36309653, 2022). "Since the presence of KRAS and RNF43 mutations in IPMNs may predict future development of advanced neoplasia from PCLs, these PCLs should be closely monitored and treated with surgery and/or targeted therapeutics." (PMID 35229994, 2022). "However, recently, covalent inhibitors targeting specific KRAS mutations - glycine 12 to cysteine (G12C) have been developed, providing an unprecedented opportunity to directly target KRAS and showing encouraging preclinical efficacy in KRAS-G12C tumor models." (PMID 35281897, 2022). "Moreover, forced overexpression of pKrasG12C in KRAS-WT mouse and human cancer cells accelerated tumor growth and restored the response to the drug." (PMID 35327394, 2022). "We tested the efficacy of three different KRAS inhibitors with divergent modes of action in vitro and in vivo using a battery of 30 natural and transduced human and murine cancer cell lines and four different methods to integrally assess tumor cell growth." (PMID 35327394, 2022).
tumor (continued). "Notably, our NI‐WB results indicated that SOX9 protein is upregulated in the tumor compared to matched mucosa, and KRAS G12D or pooled KRAS mutant had significantly higher SOX9 protein levels than WT tumors." (PMID 34919787, 2022). "Fourth, we could not assess the association between ADI and known prognostic factors, such as tumor budding, number of lymph nodes, tumor location, microsatellite instability, TILs, mutations (such as BRAF and KRAS), or histological subtypes." (PMID 35634419, 2022). "Interestingly, through the stromal cells, oncogenic KRAS (KRASG12D) has been shown to control the signaling of tumor cells." (PMID 36465388, 2022). "The immune-related mechanisms of these co-mutations are largely unknown, and our results provide new perspectives for the basic research into tumor immunobiology and immune subtyping in KRAS-driven LUADs." (PMID 35042953, 2022). "The molecular status of mutant KRAS (exon 2, codon 12/13) was analysed retrospectively by digital droplet PCR in tumour areas, venous and resection margins of resected tumours, either undergoing up-front surgery (UFS) or after NAT with a good pathological response." (PMID 35194118, 2022). "Therefore, oncogenic lncRNAs, as sponges of tumor suppressor miRNAs that target KRAS, promote cancer development via the upregulation of the KRAS oncogene." (PMID 34489556, 2022). "Interestingly, when mutant KRas expression is switched off in murine PDAC tumours, surviving cells rely on mitochondrial biogenesis, oxidative phosphorylation and autophagy for survival and re-initiation of tumour growth." (PMID 36088504, 2022). "By contrast, KRAS/CCL2/IL1B expression did not impact the survival of patients with squamous cell lung carcinoma (a tumor with low KRAS mutation frequency) (upper right)." (PMID 35327394, 2022). "These experiments suggest that tumor tissues with high KRAS expression are responsive to niraparib and that the enrichment of AKT1 during treatment might lead to drug resistance." (PMID 36230574, 2022). "Indeed, SHP2 mediates multiple RTK signals to the RAS pathway, and SHP2 inhibition inhibits RTK-mediated feedback signals in various tumor models in vitro, xenografts, and syngeneic KRAS G12C-mutant pancreatic ductal adenocarcinoma (PDAC) and NSCLC." (PMID 36508072, 2022). "In this perioperative study, we evaluate if there is a relationship between mutant allele frequency (MAF) of Kirsten rat sarcoma viral oncogene homolog (KRAS) and tumor recurrence and how that could be useful in the early detection of recurrence." (PMID 35312176, 2022). "Indeed, CDK4 inactivation led to reduced tumor development and induction of senescence in KRAS (G12V) mouse models." (PMID 35922812, 2022). "Thus, we demonstrated that the unnatural enantiomer of VC (D-VC) in combination with ATO is effective in suppressing the KRAS mutant tumour." (PMID 36619305, 2022). "Thus, the development of PDAC is highly dependent on KRAS and autophagy, again demonstrating the pro-tumor effect of autophagy." (PMID 34459894, 2022).
tumor (continued). "The seminal study testing the impact of removing functional mitochondria by suppression of the mitochondrial transcription factor A (TFAM) demonstrated a reduction of tumor burden, highlighting the requirement for mitochondrial metabolism and ROS in KRAS-driven tumor development." (PMID 36185202, 2022). "Furthermore, LDHA abrogation has been shown to reduce tumorigenesis and tumor growth and decrease the survival and proliferation of TICs in a novel inducible NSCLC mouse models in the context of KRAS or EGFR mutations." (PMID 35877003, 2022). "The association of hPDI significantly differed by KRAS status (P‐heterogeneity = .003) but not by other tumour markers." (PMID 35998061, 2022). "We also observed the enrichment of several immunological signatures, such as “TNFα/NFκB signaling” and “immune cells”, which was consistent with the immune infiltration findings, suggesting that KRAS may affect the anti-tumor immune response." (PMID 35563733, 2022). "Tumor intrinsic features, such as KRAS, NRAS and BRAF mutational status, did not interact with the survival effect of 25(OH)D levels (p = 0.773) and this was in line with a recently published review." (PMID 35681576, 2022). "KRAS regulates almost all hallmarks of pancreatic cancer, especially activating essential signaling pathways for proliferation and survival, rewiring anabolism, and suppressing immune response in the tumor microenvironment (TME)." (PMID 36230914, 2022). "However, all of the three pathogenic variants, KRAS (G12D), GNAS (R201C), and FBXW7 (R367*) remained positive in the recurrent tumor with VAFs ranging from 1.9 to 4.3%." (PMID 35255903, 2022). "One hypothesis is that only cells with KRAS G12C in the inactive conformation would be strongly inhibited by the inhibitor, and no uniform rates of inactive/active KRAS G12C could exist in a tumor." (PMID 35267628, 2022). "We further employed several transgenic mouse strains and adoptive bone marrow transfer experiments to show that effective pharmacologic KRAS blockade in vivo is dependent on the presence of CCR2+ (C-C motif chemokine receptor 2) IL-1β-secreting myeloid cells in the tumor microenvironment." (PMID 35327394, 2022). "In both analyses, the classification based solely on the mutational status of KRAS did not reveal increased resistance to chemotherapy in KRAS-mutant cell lines or tumours." (PMID 36163168, 2022). "In the previously reported in vivo studies, the BI-3406 single-inhibitor demonstrated a good inhibitory effect on KRAS G12C-mutated MIA PACA-2 cells, and the tumor volume of the two different doses of the experimental group was significantly reduced compared with the control group." (PMID 36139627, 2022). "On a biological level, cancers with KRAS G12C and STK11 co-mutations treated with adagrasib were associated with increased tumour infiltrating lymphocytes, suggesting that the drug alters the tumour microenvironment and reverses STK11-induced immunosuppression." (PMID 36284306, 2022). "In a KRAS (G12C)-mutated and CDKN2A-deficient xenograft model, the combination of MRTX849 and the CDK4/6 inhibitor palbociclib resulted in a significant reduction in tumor volume, showing considerable synergistic effect." (PMID 35922812, 2022). "However, the unique aspects of KRAS-G12D specific TCRs provided insights to how tumor infiltrating T cells recognize tumors and the potential beneficial traits for selecting therapeutically effective TCRs." (PMID 35222422, 2022).